ZNF862 (zinc finger protein 862)
Description:
May be involved in transcriptional regulation.
Synonyms: GINGF6
Tractability: PROTAC: ubiquitination databases record sites on it.
Gene: Protein-coding gene on chromosome 7 (149,838,375 to 149,867,479, forward strand). Ensembl gene ENSG00000106479.
Subcellular location: Nucleus
Subcellular location (Human Protein Atlas): Mitochondria
Gene Ontology:
Molecular function: protein dimerization activity
Biological process: regulation of DNA-templated transcription
Cellular component: nucleus
Genetic constraint (gnomAD): Loss-of-function variants: 44 observed, 60.56 expected, observed/expected ratio (o/e) 0.73, 90% interval 0.57 to 0.93. The upper end of that interval is the gene's LOEUF score, 0.93, which puts it in group 3 of 6, group 1 being the genes least tolerant of losing a copy. Missense variants: 1,063 observed, 1,097 expected, observed/expected ratio (o/e) 0.97, 90% interval 0.92 to 1.02. Synonymous variants: 446 observed, 438.07 expected, observed/expected ratio (o/e) 1.02, 90% interval 0.94 to 1.1.
Homologues: Orthologues: chimpanzee ZNF862 (99% identical), macaque ZNF862 (96% identical), dog ZNF862 (84% identical), rabbit ZNF862 (83% identical), pig ZNF862 (80% identical), guinea pig ZNF862 (76% identical). Paralogues in human: KRABD5 (4% identical).
Diseases named in the same sentence as ZNF862 in open-access papers:
ZNF862 is named in the same sentence as 3 diseases in open-access papers, as found by Europe PMC text mining. Sharing a sentence is not in itself a finding about the gene and the disease. The quoted sentences say what the papers report.
asthma (2 papers, 2015 to 2020). "The disease–gene association p-value scores (−1og10) in moderate asthma-related genes ranged from 3.2 (ZNF862) to 6 (PER2), while in severe asthma-related genes, it varied from 2.2 (TMCC1) to 6 (SLCO1B3, and WNK4)." (PMID 32512817, 2020).
gingival fibromatosis (2 papers, 2022 to 2024). "To date, genetic variants in five genes, SOS1, REST, ZNF862, ALK, and CD36, have been linked to hereditary gingival fibromatosis." (PMID 39201553, 2024).
ZNF862 also shares sentences with these, for which no sentence is quoted: allergic respiratory disease (1 paper).